IL1B (interleukin 1 beta)
Diseases named in the same sentence as IL1B in open-access papers (continued):
Sharing a sentence is not in itself a finding about the gene and the disease.
neuropathy (58 papers, 2014 to 2025). A disorder affecting the nervous system that manifests with pain, tingling, numbness, and/or muscle weakness. "In our previous studies, we have demonstrated that oligodendrocyte maturation arrest is a hallmark of the neuropathy caused by neuroinflammation that is triggered by intraperitoneal IL1B administration." (PMID 36513635, 2022). "The results of animal experiments indicated that elevated serum TNFα expression in DPN rats and elevated sciatic nerve IL-6 and IL-1β levels in diabetic rats were associated with neuropathy, this suggests that inflammatory factors may play a role in the pathogenesis of neuropathy." (PMID 39193373, 2024). "MO-administered neuropathy models of rats also showed reduced levels of serum IL-6, IL-1β, and TNF-α and reduced oxidative stress." (PMID 40297338, 2025). "In this study, palmatine was observed to inhibit TNF-induced mechanical hyperalgesia, which is consistent with previous studies showing that palmatine antagonized TNF-α and IL-1β in neuropathy models." (PMID 39458972, 2024). "Specifically, the role of the proinflammatory cytokine, IL-1β, was critical in the maintenance of neuropathy in adult rats with PAE and minor injury." (PMID 37360167, 2023). "Sciatic nerve injury in a rodent model of neuropathy upregulates P2X4R expression in spinal microglia leading to increased production of IL-1β, TNFα and IL-6." (PMID 37166584, 2023). "For instance, the CB2 agonist MDA7 prevented mechanical hyperalgesia and reduced the expression of TNF, IL-1β, and IL-6 in the spinal cords of mice with neuropathy induced by paclitaxel." (PMID 37891972, 2023). "Immunomodulators activated by MMPs include IL-1β, CXCL5, and CXCL8, whose genes were upregulated in lesional PN skin and are implicated in inflammation and neuropathies." (PMID 36619628, 2022). "They both activate glial and immune cells to release proinflammatory cytokines such as TNF-α, IL-1β, IFN-γ, and IL-6, and chemokines such CCL2 and CCL5, which cause neuronal hyperexcitability, neurodegeneration, neuropathies including neuropathic pain." (PMID 35095888, 2021). "NLRP3 inflammasome activation and IL-1β release have been observed in the DRG of mice with high-fat diet induced prediabetic neuropathy and palmitate-treated DRG neurons." (PMID 34803664, 2021). "The most important observation was the statistically significant increase in IL-1β in the neuropathy group compared with patients before and during treatment without neuropathy." (PMID 34640602, 2021). "In models, such as paclitaxel-induced neuropathy, infiltrating macrophages produce IL-1β in the DRG site, and the glycoprotein 120 of HIV-1 induces enhanced production of IL-1β in satellite glial cells." (PMID 33574810, 2020). "DRG from PAE rats with neuropathy reveal significant increases in satellite glial activation and IL-1β, while IL-10 immunoreactivity is reduced by half in PAE rats under basal and neuropathic conditions." (PMID 30961664, 2019). "So, it is possible that inflammatory cytokines such as IL-1β induced by NALP1 inflammasome significantly contribute to the painful neuropathy induced by bortezomib." (PMID 30342528, 2018). "The IL-1Ra blocks the pronociceptive effects of IL-1β and therefore has a strong analgesic effect under neuropathy." (PMID 28275350, 2017). "Increased IL-1β levels are reported in the CSF of patients suffering from different types of pain conditions, including neuropathies and chronic back pain." (PMID 24934217, 2014). "In recent years, it has become apparent that neuroinflammatory processes mediate VIPN, and specifically, that vincristine leads to activation of the NLRP3 inflammasome in monocytes, which in turn affects the release of IL‐1β that drives neuropathy symptoms, such as sensory and motor disturbances." (PMID 40104043, 2025). "TNF-α, IL-1β, and IL-6 play a considerable role in the pathogenesis of neuropathy." (PMID 40703750, 2025).
neuropathy (continued). "In addition, we demonstrated that PTL also significantly reduced the pro-inflammatory cytokine IL-1β after LPS induction, similar to a study in a rat model for neuropathy or in different studies in cell culture." (PMID 40100917, 2025). "Moreover, a single subcutaneous administration of ozone decreased allodynia, caspase expression and IL-1β immunoreactivity in orbitofrontal cortex astrocytes in mice with induced neuropathy." (PMID 37685060, 2023). "Accumulating evidence implicates that P2x4 potentiates P2x7-dependent release of proinflammatory cytokines including IL-1β, IL-6 and Tnfα in both central and peripheral nervous systems, leading to neuroinflammation, which contributes to induce neuropathy and abnormal nociception." (PMID 35332157, 2022). "In addition, neutrophils are known to produce pronociceptive mediators, including IL-1β, while microglia and macrophages promote the recruitment of neutrophils and participate in the cascade of events leading to neuropathy." (PMID 34681732, 2021). "For example, administration of antibodies to interleukin I-receptor (IL-lR) or its genetic deletion or overexpression of interleukin receptor antagonist (IL-RA) reduce pain behavior in mice with experimental neuropathy thereby implicating IL-1β in the onset of neuropathic pain." (PMID 35295524, 2021). "Thus, it is assumed that stress increases TNF‐α and, possibly to a lesser extent, IL‐1β levels in the PFC and can cause neuropathy, but BHB suppresses neuroinflammation and exerts a neuroprotective effect." (PMID 32125791, 2020). "The current report also supports the possible involvement of other complimentary cytokines such as TNFα, in which it has been shown to be upregulated by IL-1β, can act synergistically with IL-1β during neuropathy and is involved in the induction and maintenance of allodynia." (PMID 30961664, 2019). "Thus, the inhibition of IL-1β by melatonin reported here suggests that the neuroinflammatory process in CMT1A neuropathy involves both NF-κB and NLRP3 inflammasome." (PMID 29036910, 2017). "Also, in a model of isolation stress combined with a model of cardiac arrest surgery, and under conditions of maternal deprivation combined with spinal nerve ligation (SNL) neuropathy model, mRNA for Il-1β was shown to be upregulated in the hippocampus." (PMID 28536509, 2017). "We have shown that the inhibition of NF-κB with a potent inhibitor, parthenolide, not only diminished the symptoms of neuropathy but also potentiated morphine analgesia and reduced the levels of pro-inflammatory factors produced by microglia (IL-1β, IL-18, NOS2)." (PMID 28491822, 2017). "This may suggest that the mechanism of IL-1Ra activation relies on the P2X4R-mediated pathway and that this molecule, along with pronociceptive IL-1β (IL-1Ra blocks its activation), plays a key role in neuropathy development." (PMID 28275350, 2017). "Our previously published results showed that inhibition of NF-κB by its potent inhibitor, parthenolide, diminished symptoms of neuropathy, potentiated morphine analgesia, and diminished pronociceptive markers of microglial cell polarization (IL-1β, IL-18, and iNOS)." (PMID 28573049, 2017). "IL-10 inhibits the release of IL-1β and IL-6 and plays role in neuropathy." (PMID 26090236, 2015). "A previous study has demonstrated that chemotherapy-induced neuropathy is associated with the induction of proinflammation mediators (such as IL-1β and TNF-α) in the dorsal root ganglion (DRG), which may ultimately cause the initiation and maintenance of persistent neuropathy." (PMID 34366713, 2021). "Previous studies reported that in the CCI-induced neuropathy model, the TNF-α, IL-1β signals, and infiltration of CD68+ inflammatory cells induced a partial decrease after nerve release." (PMID 35893792, 2022).
neuropathy (continued). "Microglia are activated by neurotransmitters secreted from the terminals of presynaptic neurons in the dorsal horn of the spinal cord, and neuropathy is induced by the secretion of various inflammatory factors (TNF-α, IL-1β, and IL-6)." (PMID 34073390, 2021). "Mean values for IL-1β, TNF, TGF-β, and IL-17 cytokine concentrations were higher in the Group of leprosy neuropathy in combination with neural pain than in the other Groups." (PMID 32038662, 2020). "In animals, proinflammatory cytokines IL-1α, IL-1β, and TNF-α are known contributors to the pathogenesis of neuropathy." (PMID 32908447, 2020). "TNF-α, IL-1β and NF-κB levels in sciatic nerve of PSNL control rats were significantly increased (p < 0.05) after induction of neuropathy as compared to normal as well as sham control rats." (PMID 28694757, 2017). "As for the possible mechanism of neuropathy in AML, previous studies have found that bone marrow nerve injury reduced the expression of IL-1β and TGF-β." (PMID 27016413, 2016). "We found that IL6, TNF, CXCL8, IL1B and ERK1/2 were the top genes in terms of the number of connections in platinum-induced neuropathy, suggesting either direct or indirect interactions with nervous tissue leading to CIPN after exposure to platinum compounds." (PMID 26269716, 2015). "In the context of neuropathy, up-regulation of COX-2, iNOS, TNF-α, and IL-1β via the NF-κB and MAPK signaling cascades induces the infiltration of inflammatory cells, including neutrophils and monocytes, into the sciatic nerve and spinal cord of neuropathic mice." (PMID 40703750, 2025). "Neuropathy in the skull bone marrow of recipients of VF BM correlated with a significant reduction in Nestin-GFP + MSC numbers, whereas comparable numbers of Nestin-GFP + MSC were observed in recipients of VF;IL-1β-/ and WT bone marrow." (PMID 36100613, 2022). "Particularly, increased levels of IL-1β, IL-6 and TNF-α in ALS patients compared to controls or patients with other neuropathies have been reported, suggesting that the modulation of these inflammatory mediators may ameliorate the course of the disease." (PMID 36362341, 2022). "At the same time, the plasma concentration of IL-1β in patients with neuropathy was significantly increased compared with patients without PN before and during treatment." (PMID 34640602, 2021). "IL-1β levels are increased in the cerebrospinal fluid (CSF) of patients with complex regional pain syndrome and in spinal cords obtained post-mortem from patients with painful HIV related neuropathy." (PMID 35295524, 2021). "Our analysis identified increased concentrations of CCL2, IL-1β, and IFN-γ in plasma of MM patients during treatment, both with and without symptoms of PN, compared with untreated neuropathy-free MM patients." (PMID 34640602, 2021). "Here, we report anatomically distinct protein profiles for IL‐10, IL‐1β, and MCP‐1 under conditions of neuropathy, which has not been widely examined." (PMID 32977358, 2020).
anemia (57 papers, 2012 to 2026). A reduction in the number of red blood cells, the amount of hemoglobin, and/or the volume of packed red blood cells. "Here, we infer that strain-directed immunomodulation contributes to differences in anemia severity, with pro-inflammatory cytokines IL-1β, IL-6, IFN-γ, and TNF-α implicated." (PMID 41602558, 2026). "Collectively, the results allow the proposition that rs1149222 fosters an IL-1β-dominated milieu that, through hepcidin induction and erythropoietin suppression, yields the mild inflammation-associated anemia noted in heterozygotes." (PMID 40869618, 2025). "Elevated plasma levels of IL-1β in association with anaemia, pyrexia and exacerbated parasitaemia occurred in patients co-infected with Plasmodium falciparum and E. vermicularis or multiple helminth species." (PMID 39135121, 2024). "The results of the ROC analysis of HPC, as was the case in cytokines IL-1β and TNFα, ranged between 0.6 and 1.0, indicating a potential diagnostic value for clinical prognosis for patients with age-associated anemia." (PMID 37240288, 2023). "The IL1B −511A allele was associated with an increased risk of severe malarial anemia and reduced levels of IL-1β." (PMID 23316245, 2012). "Furthermore, our mechanistic in vitro studies indicate that Pi elevations induce hepatic production of IL6 and IL1β to increase hepcidin expression in hepatocytes, a potential causative link between hyperphosphatemia, anemia, and skeletal muscle dysfunction." (PMID 35302487, 2022). "In consistence with our findings in KD, IL-1β pathway stimulation leads to excess production of hepcidin, which could be causative to anemia of inflammation." (PMID 29721174, 2018). "The higher inflammatory response in piglets without additional iron in the diet in this study is consistent with previous studies in which low iron status led to increased pro-inflammatory cytokines (including IL-1β, IL-6, and TNF-α) in iron deficiency anemia." (PMID 39296492, 2024). "The biological plausibility of bleeding and anemia in VL cases is correlated with increased levels of pro-inflammatory cytokines: IL-8, IL-1β, IL-10, and IFN-γ, which are also exacerbated in cases of bacterial coinfection." (PMID 38422344, 2024). "IL-1β associated with reduced EPO synthesis and blockade of IL-1β is associated with reduced incidence of anemia and improvement of hemoglobin levels." (PMID 38675885, 2024). "The highest average odds ratio was observed for IL-1β (AUC = 0.523, OR = 72.374, 95%Cl 19.688–354.366), which indicates this cytokine as a good marker of inflammation-related anemia." (PMID 37240288, 2023). "Chronic inflammation produced by daily injection in young mice of 0.5 μg IL-1β for 20 days mimics features of blood aging, including myeloid cell expansion, decreased lymphopoiesis, anemia and thrombocytosis as well as impaired HSC engraftment." (PMID 36650381, 2023). "The results of the ROC and OR analysis of age and inflammatory variables, i.e., IL-1β, TNFα and HPC, indicate a potential diagnostic value for clinical prognosis for patients with age-associated anemia." (PMID 37240288, 2023). "The cytokine-induced inhibition of erythropoiesis is regarded as an important mechanism for the development of anemia in cancer patients, TNFα in particular but also other inflammatory regulators, including IL1β, IL6, IL10 and IFNγ, probably contribute." (PMID 35160156, 2022). "Laboratory investigation indicated mild anaemia and elevations of leucocytes, interleukin 1 beta, tumor necrosis factor alpha." (PMID 34847873, 2021). "In patients receiving canakinumab—an antibody that is targeting IL-1β—hsCRP and IL-6 levels decreased while hemoglobin levels increased concomitantly in patients with baseline anemia." (PMID 34458328, 2021). "Erythropoietin and interleukin 1 beta (IL-1β), which are increased in condition of anemia and inflammation respectively, are two potent inducers of Fgf23 at the transcriptional level." (PMID 34149625, 2021).
anemia (continued). "Maternal anemia was also associated with cytokine responses in cord (particularly for MDP and LPS), with higher IL-10, IL-1β, MDC, TNF, IL-12p70, IL-12p40 responses following PRR stimulation." (PMID 32765436, 2020). "The LPS + PM group showed increased BALF leukocytes, characterized by increased macrophages, increased IL-1β and IL-6 levels, anemia and thrombocytopenia." (PMID 32943719, 2020). "IL-10 suppresses inflammation by suppressing various cytokines, including IL-1β and TNFα, which is also a mechanism involved in down-regulating hepcidin expression and alleviation of anemia." (PMID 30836628, 2019). "Inflammatory markers associated with greater severity of anaemia in both patient groups included increasing CRP, IL-1β and IL-6 concentrations." (PMID 26792471, 2016). "Whole blood Nampt/PBEF/visfatin tended to be elevated in patients with metastatic cancer or anemia and correlated with inflammatory indices, of which IL1β, IL8, and hematocrit explained 60% of its variability." (PMID 26075243, 2015). "Nampt/PBEF/visfatin expression in nontumor tissue, both mRNA and protein, increased in patients with metastatic disease and mild anemia, and, on transcriptional level, correlated with HIF1α, IL1β, IL8, CCL2, and CCL4 expression." (PMID 26075243, 2015). "Significantly increased IL-1β transcript levels and increased secretion of TNF have been associated with placental malaria and (for TNF) with a heightened risk of severe anaemia and LBW." (PMID 24465935, 2014). "The role of IL‐1β in the development and pathological etiology of anemia has been reported." (PMID 39240033, 2024). "Thus, TNFα, IL-1β, IL-6 and IFN-γ seem to be responsible for impaired EPO synthesis in the development of anemia associated with inflammation." (PMID 37240288, 2023). "The etiology of CKD-associated anemia is multifactorial and includes absolute iron deficiency and functional iron deficiency, with the latter caused by inflammatory cytokines including interleukin-6 (IL6) and interleukin-1β (IL1β)." (PMID 35302487, 2022). "Finally, module 3 is formed by Ang-2 and the proinflammatory cytokine IL-1β negatively associated with haemoglobin, haematocrit, and RBC numbers (anaemia markers)." (PMID 34585667, 2021). "However, the association observed here seems to be independent from inflammation as well since IL1β was Nampt/PBEF/visfatin independent predictor in addition to anemia/hematocrit." (PMID 26075243, 2015). "We hypothesized that in H. pylori infected children without the known common causes of ID, increased gastric concentrations of IL-1β and/or TNF-α could be predictors for low blood concentrations of ferritin and haemoglobin, markers of early depletion of iron stores and anaemia, respectively." (PMID 23451225, 2013). "In particular the production of endogenous pyrogens such as TNF, IL-1β and IL-6 following IFN-γ stimulation of monocytes/macrophages may be responsible for fever induction and sustained IL-1β production may be associated with anaemia." (PMID 23046548, 2012). "Anemia can stimulate the production of pro-inflammatory cytokines such as tumor necrosis factor-alpha (TNF-α), interleukin-1 beta (IL-1β), and interleukin-6 (IL-6)." (PMID 40486649, 2025). "Treatment-induced tissue damage elevates circulating mediators (C-reactive protein [CRP], IL-6, interleukin-1β [IL-1β], interferon [IFN], tumor necrosis factor-α [TNF-α] potentially mediating central fatigue through anemia and cachexia pathways." (PMID 40496975, 2025). "Oxidative stress disrupts tight junction proteins such as occludin and claudin, leading to increased BBB permeability.Anemia and ischemia activate microglia and astrocytes, releasing pro-inflammatory cytokines (e.g., TNF-α, IL-1β) and chemokines." (PMID 40486649, 2025). "On the other hand, the circulating levels of IL-1β, IL-8, CXCL10, IL-6, CCL4, IL-1RA and CCL2 displayed an inverse behavior, with rising levels being proportional to increases in anemia severity." (PMID 37143662, 2023).